CTSB (cathepsin B)
Diseases named in the same sentence as CTSB in open-access papers (continued):
Sharing a sentence is not in itself a finding about the gene and the disease.
tumor (continued). "Furthermore, it identifies that cathepsin B+ tumor‐associated macrophages may over‐activate CD8+ T cells in MIA, leading to an enrichment of granzyme K+ senescent CD8+ T cells, indicating the possibility of malignant progression behind the indolent appearance of MIA." (PMID 37991139, 2023). "The protein complex annexin A2-S100A10 heterotetramer (AIIt) can act as a binding protein for CTSB on the tumor cell surface and localizes on the extracellular surface, where it enhances the activation of proteases." (PMID 37576397, 2023). "Although stromal cells and normal epithelial cells nearby the tumors can express cathepsin B, the expression is often highest along the tumor’s advancing edge." (PMID 36574159, 2022). "To avoid the influence of tumor heterogeneity, we also compared the effect that CTSB have on the OS time of LGG and HGG respectively, and this phenomenon was more obvious in HGG." (PMID 35277559, 2022). "Extracellular matrix glycoproteins such as Laminin-γ2 and proteolytic enzymes such as MMP1, CTSS & CTSB were radically up-regulated under acute acidotic stress, but all become less expressed when tumor cells steadily adapted to extended extracellular acidity." (PMID 35410237, 2022). "Cathepsin B role in cancer is attributed to extracellular matrix degradation resulting in tumor invasion and metastasis." (PMID 35260133, 2022). "We found that CTSB secreted by tumor significantly promoted the activation of neutral caspase-11/GSDMD cells IVM directed at SDMX has greatly inhibited SDMX oligarchy and the subsequent GSMX core network." (PMID 36132145, 2022). "Cathepsin B, a lysosomal cysteine cathepsin, has been found to be hyper-secreted in the tumor environment of various solid tumors." (PMID 36195918, 2022). "Once CTGP@DOX encountered the high secretion of cathepsin B around tumor cells, it dissociated upon cathepsin B cleavage and reassembles into nanofibers on the cell membrane by targeting the hydrophobic 16-carbon alkyl chain through the cell membrane." (PMID 35186883, 2022). "Accordingly, several peptide substrates of cathepsin B have been exploited for tumor-targeted drug delivery, which showed promising outcomes for the treatment of tumors in multiple preclinical trials." (PMID 35456562, 2022). "The CTSB on tumor cells surface can remove the autoreactive lymphocytes and degrade these cytotoxic effector molecules (such as IgG and chemokines CXCR3, CXCL9, CXCL10) synthesized from tumor-suppressive infiltrating immune cells." (PMID 35277559, 2022). "Among them, Module2 (highly express RNASE1, C1QA, CD163, CD14, C1QC, FCGRT, and MS4A7) and Module10 (highly express APOC1, CTSB, CTSL, and TYROBP) are more likely to display the characteristics of tumor-associated macrophages (TAMs)." (PMID 35990663, 2022). "Down-regulation of CTSB significantly inhibited the proliferation, invasion and tumor angiogenesis of GBM8." (PMID 35277559, 2022). "The 4-mer peptide GFLG can be specifically hydrolyzed by cathepsin B to trigger drug release from drug carriers for effective tumor therapy." (PMID 36348391, 2022). "Several effective CTSB-responsive antitumor drug delivery systems have been developed by capitalizing on differences in CTSB concentrations and activities between tumor and healthy tissues." (PMID 36080733, 2022). "The branches of the dendritic polymers and PTX were conjugated to the polymer via a short peptide Gly-Phe-Leu- Gly that was sensitive to cathepsin B, a lysosomal cysteine protease overexpressed in tumor cells." (PMID 36501528, 2022). "Many clinical results have demonstrated that cathepsin B is involved in the degradation of the ECM for tumor progression and metastasis and is thus overexpressed in most malignancies." (PMID 35456562, 2022). "It is worth mentioning that this achievement is best shown in the in vivo setting, as several proteases that are known to degrade PGA to some extent, such as Cathepsin B, S, L and others 46, 68 are present in the tumor microenvironment." (PMID 36168618, 2022).
tumor (continued). "The FRRG sequence is a substrate for the cathepsin B, which is a promising cancer biomarker overexpressed specifically in tumor cells compared to normal cells." (PMID 36297566, 2022). "Cathepsin B role in cancer is related to basement membrane and extracellular matrix protein degradation, a mechanism which is responsible for metastasis and tumor invasion of cancer cells." (PMID 35260133, 2022). "A strong correlation between cathepsin B expression and tumor angiogenesisinvasionand metastasis has been widely described in the literature." (PMID 35814405, 2022). "Similar release patterns have also been observed for the Fn-caged Lap in the nanoassemblies that the combined treatment of pH 5.5 and cathepsin B has triggered the fastest Lap release, validating their on-demand drug release capability in tumor lysosomes." (PMID 36167857, 2022). "CTSB belongs to the cysteine protease family that affects tumour growth and invasion through interaction with cellular proteins." (PMID 35459137, 2022). "The new carrier-free prodrug nanoparticles are prepared by self-assembly of cancer-specific prodrugs, constructed with tumor-overexpressed cathepsin B-specific cleavable peptide FRRG and DOX (FRRG-DOX)." (PMID 36195911, 2022). "Compared to CtsB, the increase in STFA expression in cancer tissues was higher than in control specimens, decreasing the CTSB/STFA ratio in the tumor." (PMID 35563761, 2022). "Bengsch and colleagues demonstrated in mice models of breast cancer that the overexpression of cathepsin B increased tumor cell invasion favoring proteolytic extracellular matrix degradation." (PMID 36364419, 2022). "Based on relevant literature, CTSB acts as a bridge between ER stress and necroptosis: ER stress activated CTSB in isolated pancreatic acinar cells during AP; and excessive CTSB led to necroptosis in tumor cells, by processing of Bid to attack mitochondria." (PMID 36059491, 2022). "While cathepsin B resides in lysosomes under normal physiological conditions, it is highly expressed on the surface of cancer cells and can be used for tumor targeting." (PMID 33802262, 2021). "Then the tumor size and weight generated by CTSB-shRNA HL-60 cells and scramble cells were compared." (PMID 33628106, 2021). "It has been shown before that IL‐6 facilitates CTSB expression in monocytes in tumor tissue, suggesting a potential connection between physical activity‐induced IL‐6 levels and CTSB." (PMID 33655551, 2021). "Tumor type-specific deviations in ACE2/protease co-expression were less prominent for CTSB, CTSL, and FURIN compared to TMPRSS." (PMID 33707526, 2021). "In contrast, CTSB deletion leads to delayed tumor onset, slower growth rate, and reduced metastasis volume." (PMID 32385587, 2021). "Increased expression of CDH2, CTSB, ACTA2, MMP2 and ZEB1 was associated with increased myometrial invasion, and expression of CTSB and MMP9 was significantly associated with tumor recurrence." (PMID 34936030, 2021). "Again, a reduced abundance of CREG1 was evident in tumor lysates from mice with transgenic overexpression of human CTSB (long exposure)." (PMID 32385587, 2021). "The results showed a smaller tumor volume and less tumor weight in CTSB-shRNA group than scramble group." (PMID 33628106, 2021). "The response of the formulation to the presence of cathepsin B, a proteolytic enzyme that is overexpressed and secreted in the tumour microenvironment of many solid tumours, was assessed." (PMID 33245955, 2021). "Since then, further evidence for stromal, i.e., macrophage, CTSB in tumor promotion has been accumulating." (PMID 32385587, 2021). "For instance, hyaluronidase, matrixmetalloproteinases, and cathepsin B are overexpressed in tumor cells." (PMID 34805129, 2021). "In summary, we proposed achieving the effective and safe chemotherapy with cathepsin B-overexpressed tumor cell activatable albumin-binding doxorubicin prodrug (Al-ProD) via albumin-mediated drug delivery." (PMID 35056979, 2021).
tumor (continued). "Proteolytic enzymes (e.g., collagenase, trypsin, plasmin, and cathepsin B) and matrix metalloprotease expressed in tumor cells facilitate tumor spread by denaturalizing the extracellular matrix, migration, and chemotaxis, also called intravasation." (PMID 34287274, 2021). "Among the papain family of cysteine proteinases, cathepsin B (CTSB) is reported to participate in tumor cell proliferation, angiogenesis, and invasion, and has been identified as a target of HIF-1α." (PMID 34445307, 2021). "Herein, we propose cathepsin B-overexpressed tumor cell activatable albumin-binding doxorubicin prodrug, Al-ProD, which can effectively deliver anticancer drugs by in situ albumin-mediated passive targeting with minimal side effects." (PMID 35056979, 2021). "High level of Cathepsin B was correlated with dissociation from extracellular matrix and enhanced movement of tumor cells." (PMID 34512164, 2021). "Herein, we propose cathepsin B-overexpressed tumor cell activatable albumin-binding doxorubicin prodrug, Al-ProD, that consists of a albumin-binding maleimide group, cathepsin B-cleavable peptide (FRRG), and doxorubicin." (PMID 35056979, 2021). "In conclusion, we were able to establish CTSB as a key determinant of CREG1-mediated tumor growth suppression." (PMID 32385587, 2021). "In vivo results show that the tumor can be imaged by the L-SR15, due to the selectively activation by the cathepsin B in the tumor site." (PMID 34805129, 2021). "In terms of tumor biology, CTSB was the first among the cysteine cathepsins shown to impair lung colony formation upon tail-vein injection of CTSB proficient cancer cells, in otherwise CTSB-deficient mice." (PMID 32385587, 2021). "With screening, among these cytokines, Cathepsin B was considered as an invasion and metastasis promoter for tumor in generous studies 15-18." (PMID 34512164, 2021). "MMTV-PyMT crossed with cathepsin B knockout mice showed a delay in tumor onset and decreased metastasis compared to the WT mice." (PMID 34043703, 2021). "The Al-ProD binds to in situ albumin, and albumin-bound Al-ProD indicates high tumor accumulation with prolonged half-life, and selctively releases doxorubicin in cathepsin B-overexpressed tumor cells, inducing a potent antitumor efficacy." (PMID 35056979, 2021). "Our study highlights CREG1 as a key player in tumor–stroma interaction and suggests that cathepsin B sustains malignant cell behavior by reducing the levels of the growth suppressor CREG1 in the tumor microenvironment." (PMID 32385587, 2021). "The linker showed similar stability in the circulation; however, in comparison to the traditional Val-Cit dipeptide, it showed superior cathepsin B specificity in tumor-bearing mice." (PMID 34440076, 2021). "On the other hand, it has been reported that cathepsin B in vasculature increased dramatically during the degradation of vascular basement membrane in tumor-mediated angiogenesis." (PMID 31968635, 2020). "In meninges, the downregulation of CTSB and matrix metalloprotein-9 inhibited the proliferation of tumors and reduced tumor cell proliferation, invasion, angiogenesis, and downstream kinase signaling pathway activation." (PMID 33238959, 2020). "The obtained ultrasmall Au NPs showed enough colloidal stability and cathepsin B-responsive surface change, leading to selectively uptake by cancer cells in vitro and accumulation to tumor sites in vivo." (PMID 32373207, 2020). "A cathepsin B-responsive PEGylated gemcitabine-containing system was developed to target tumor microenvironments." (PMID 32580366, 2020). "Higher levels of CTSB have been demonstrated in neoplastic thyroid disease compared to non-neoplastic disease." (PMID 33333840, 2020). "The Au NPs exhibited enough colloidal stability and cathepsin B-responsive surface change, leading to selectively uptake by cancer cells in vitro and accumulation to tumor sites in vivo." (PMID 32373207, 2020).
tumor (continued). "While it is known that secreted CTSB significantly alters the tumor microenvironment during invasion, its mechanism of action and associated intracellular signaling pathway(s) have not yet been determined." (PMID 33333840, 2020). "Dendrimer-methoxy poly (ethylene glycol) doxorubicin (DOX) conjugates were also synthesized with the aid of a cathepsin B-cleavable peptide for anticancer targeting, as cathepsin B is overexpressed in tumor microenvironments." (PMID 32580366, 2020). "Targeting cathepsin B has been found not only to reduce the development of malignant melanotic tumors, but also to inhibit tumor growth and metastasis in mice." (PMID 33335896, 2020). "These proteases, including MMP-3, MT1-MMP (MMP-14), cathepsin B and cathepsin D, have been reported to play important roles in cancer invasion, in vivo tumor growth and distant metastasis." (PMID 33110168, 2020). "The linker to the monoclonal antibody is stable in extracellular fluid, but the conjugate is cleaved by cathepsin B upon entry into the tumour cells." (PMID 32152502, 2020). "This suggested that TSPN exerted an anti-tumor effect by downregulating the expression of the CTSB gene." (PMID 33238959, 2020). "Acidification also activates tumor-cell proteinases, such as matrix metalloproteinases-9, cathepsin B and hyaluronidase-2, which degrade the surrounding matrix and promote tumor cell migration." (PMID 33153193, 2020). "AKT inhibitor capivasertib (AZD5363) was encapsulated into cathepsin B-responsible nanoparticles (NPs) for tumor-specific delivery." (PMID 32106632, 2020). "The result of quantitative fluorescent PCR indicated that compared with the tumor-bearing group, the expression of the CTSB gene after TSPN gavage treatment reduced and was more significant with an increase in the dose." (PMID 33238959, 2020). "The expressions of three tumor-associated proteins, TGF-β, CTSB and FSTL1, were examined using immunohistochemical staining and Western blotting." (PMID 32050622, 2020). "Both isolates required the lysosomal protease cathepsin B for complete execution of the tumor cells." (PMID 32047722, 2020). "The result of quantitative fluorescent PCR indicated that the expression level of CTSB mRNA reduced after TSPN gavage treatment compared with that in the tumor-bearing group, and was more significant with an increase in the dose." (PMID 33238959, 2020). "Extracellular matrix (ECM) and intracellular collagen IV can be degraded by cathepsin B, stimulating tumor invasion, metastasis, and the formation of vessel-like structures in vivo." (PMID 32733461, 2020). "The results of Western blot analysis and indirect immunofluorescence indicated that the expression of CTSB protein reduced after TSPN gavage treatment in a dose-dependent manner compared with the tumor-bearing group." (PMID 33238959, 2020). "On the other hand, cathepsin B can activate a variety of growth factors or increase its release, promoting angiogenesis and tumor proliferation." (PMID 32727598, 2020). "In this regard it was shown in a model where tumor cells were injected inside the sciatic nerve, that preferentially macrophages promoted further nerve invasion through cathepsin B." (PMID 32013137, 2020). "The role of the CTSB gene in tumor development and progression (initiation, proliferation, angiogenesis, invasion, inflammation, apoptosis, and metastasis) was comprehensively investigated using a mouse model." (PMID 33238959, 2020). "Similar to the dysregulated Cathepsin B expression in the tumor microenvironment inducing tumor progression, Cathepsin K over-expression is associated with cancer metastatic disease, indicating its potential diagnostic and prognostic value." (PMID 32927648, 2020). "In a proposed model for tumor cells, activation of receptor-bound-pro-CTSB (AnxA2/CTSB) at the caveolae triggers the uPA/plasminogen/plasmin proteolytic cascade that culminates with MMP activation and ECM breakdown." (PMID 33379277, 2020).
tumor (continued). "Among the three xenograft models LKO, CTSBwt/hi, and CTSBN298A, sunitinib treatment was least effective in retarding tumor growth in the setting of wild-type CTSB overexpression." (PMID 30796200, 2019). "Higher levels and altered localization of cysteine cathepsins, including CTSL and CTSB within the tumor microenvironment, are essential for tumor growth, invasion, and neovascularization." (PMID 31824841, 2019). "CTSB also plays an important role in tumor angiogenesis through proteolytic remodeling of the extracellular matrix (ECM), a key step in vessel sprouting during angiogenesis." (PMID 30796200, 2019). "In tumor tissue, cathepsin B seems to be expressed predominantly in areas bordering the extracellular matrix." (PMID 31484396, 2019). "The mode of action of this release mechanism requires increased activity of cathepsin B to ensure the triggering release close to the tumor." (PMID 31484396, 2019). "Subsequently, we analyzed the data set on the cathepsin B mRNA expression for the impact of the tumor stage." (PMID 31484396, 2019). "Both CTSB knockdown constructs showed significantly inhibited tumor cell colony formation when compared to vector control cell lines (p < 0.01)." (PMID 30796200, 2019). "Survival analysis was performed on tumor samples in the upper quartile (high CTSB) and lower quartile (low CTSB) of CTSB expression." (PMID 30796200, 2019). "The enzymatic activity of CTSL and CTSB was assayed in tumor and control gallbladder tissues using a synthetic fluorogenic substrate CBZ-PheArg-NMec and expressed as RFU/min/mg protein." (PMID 31824841, 2019). "In this study, we used proteomic and genomic approaches, along with systems biology techniques, to show the key role that CTSB plays in RCC tumor growth and resistance to TKI therapy." (PMID 30796200, 2019). "Overexpression of wild-type CTSB in the shCTSB2 line mitigated the reduction in tumor growth seen in shCTSB2 tumors, such that tumor growth was not significantly different from that of the vector control group (P = 0.29)." (PMID 30796200, 2019). "It is thought that CTSB participates in remodeling of connective tissues during tumour growth, invasion and metastasis." (PMID 31467500, 2019). "The vast influence of cathepsin B on various aspects of tumor metastasis makes it an attractive target for cancer therapy." (PMID 30818851, 2019). "Invasive tumor growth and lymph node metastasis are closely related to the proteolytic enzymes MMPs, urokinase-plasminogen activator, and cathepsin B, D, and L30–34." (PMID 31601869, 2019). "The anti-uPAR ADC that resulted in tumor regression comprised an MMAE payload with a cathepsin B cleavable linker, 2G10-RED-244-MMAE." (PMID 31694242, 2019). "Cathepsin B was found to be overexpressed in tumour cells, and was mainly involved in the metastasis and invasion of tumour cells." (PMID 30781696, 2019). "Cathepsin B is an important class of enzymes related to tumor progression and is a candidate target for molecular therapy." (PMID 31737654, 2019). "With the intention to confirm presence of the peptidase in malignant transformed cells, the number of cathepsin B mRNA copies was determined in tumor entities originating from cervix, breast, endometrium, and ovary." (PMID 31484396, 2019). "To evaluate the impact of CTSB on tumor growth in vivo, we generated tumor xenografts with our 786-O CTSB knockdown cell lines." (PMID 30796200, 2019). "At the same time cathepsin B promotes autophagy and cannibalism allowing tumor cells to recycle nutrients and maintain a proliferative and infiltrative phenotype." (PMID 30949483, 2019). "We therefore tested the role of CTSB in regulating tumor-initiating stem cells by assaying tumor cell sphere formation." (PMID 30796200, 2019). "The impact of tumor progression on cathepsin B mRNA expression levels was assessed considering the reported tumor stage." (PMID 31484396, 2019).